INS (insulin)
Diseases named in the same sentence as INS in open-access papers (continued):
Sharing a sentence is not in itself a finding about the gene and the disease.
Atrophy (14 papers, 2013 to 2025). Any weakening or degeneration, especially through lack of use. "Transgenic, αKlotho-deficient mice exhibit pancreatic islet atrophy with reduced pancreatic insulin mRNA and protein levels and serum insulin concentrations." (PMID 34208131, 2021). "It was involved in the loss of neurogenin-3 (Ngn3)-positive endocrine progenitor cells, pancreatic atrophy, and reduced insulin sensitivity to endogenous glucose production leading to the reduction of insulin secretion." (PMID 35480487, 2022). "It was involved in the loss of neurogenin-3 (Ngn3)-positive endocrine progenitor cells, pancreatic atrophy, and a reduced insulin sensitivity to endogenous glucose production leading to the reduction of insulin secretion." (PMID 32329795, 2020). "Type II muscle fibers, which are less dependent on metabolic insulin action, are reduced more than type I fibers in age-related muscle atrophy." (PMID 31013777, 2019). "They suggested that cancer-related muscle atrophy may be correlated with lipid metabolism damage, potentially due to insulin insensitivity." (PMID 39014376, 2024). "To test if improved cell metabolism by sustained activation of the insulin/mTOR pathway prolongs cone survival in the sodium iodate induced model of RPE atrophy, we constitutively activated the pathway in cones at two separate junction points downstream of the insulin receptor." (PMID 26883199, 2016). "Another interesting finding was thymic atrophy in diabetic mice, and insulin therapy failed to alleviate the pathological changes." (PMID 37311905, 2023). "That said, we investigated the effects of the dexamethasone model of muscle atrophy on BCAA utilization and found that Dex restored extracellular BCAA to control levels, which were otherwise reduced in insulin-resistant cells not treated with Dex." (PMID 40422898, 2025).
blood pressure (14 papers, 2014 to 2025). "The protection afforded by γOz in both organs occurred even with the maintenance of high blood pressure, blood glucose, and insulin levels, as showed by the maintenance in proteinuria and cardiac function in the HSF + γOz group." (PMID 29186059, 2017). "A relatively small number of patients (such as those adjusting insulin doses or high blood pressure medications) will be using data for self-management; these individuals are most likely to be interested in reminders or alerts." (PMID 26290186, 2015). "Following a 12-week research period, there was an elevation in FBG and insulin levels, high blood pressure in the fructose group, as well as concomitant alterations in insulin-stimulated glucose uptake, insulin binding, and GLUT4 expression in their adipocytes." (PMID 40647906, 2025). "Consistent with previous studies, our investigation indicated that the 12-weeks PCA administration elicited the decreases in high blood pressure together with restoring vascular function by improving endothelium-dependent vasorelaxation induced by insulin and IGF-1 in aging SHR." (PMID 30934575, 2019). "Besides the insulin I must take my medications for high blood pressure." (PMID 28828389, 2017).
cholelithiasis (14 papers, 2011 to 2025). The presence of crystallized deposits forming in the gallbladder or biliary tree, primarily composed of cholesterol, bilirubin, and bile. "For example, the aMED and HEI-2015 diets are rich in dietary fiber, which may reduce cholelithiasis risk by enhancing the production of short-chain fatty acids, lowering cholesterol saturation in bile, and improving insulin resistance." (PMID 39399528, 2024). "Additionally, their study reported that patients with high cholesterol, triglycerides, and insulin serum concentrations had a significantly higher cholelithiasis occurrence than in the control group." (PMID 39195832, 2024). "The serum concentrations of total cholesterol (p < 0.001), triglycerides (p < 0.001), and insulin (p = 0.030) were significantly higher in dogs with cholelithiasis compared with those in healthy dogs, but glucose levels did not significantly differ between controls and patients (p = 0.524)." (PMID 29088261, 2017). "We summarized the important feedback mechanisms of FXR and GLP-1 in cholesterol metabolism and insulin sensitivity, discussed the possible important role of GLP-1 in gallbladder contraction disorders, and examined the relationship between cholelithiasis and metabolism." (PMID 35454138, 2022).
Down syndrome (14 papers, 2012 to 2025). "Down syndrome (DS) is a genetic disorder caused by trisomy of chromosome 21 that also displays β-cell mitochondrial dysfunction and reduced insulin secretion in humans." (PMID 27195491, 2016). "However, children with chromosomal anomalies, specifically children with Down syndrome, were at an increased risk of > 1 insulin/insulin analogue prescription compared with reference children." (PMID 36869270, 2023). "Mitochondrial dysfunction and reduced insulin secretion are also observed in β-cells of humans with the most common human genetic disorder, Down syndrome (DS, Trisomy 21)." (PMID 27195491, 2016). "Our study showed that the false positive screening tests for Down syndrome are increased in women with PGDM using insulin." (PMID 26237386, 2014). "Interestingly, islets derived from fetal Down syndrome (DS) tissue exhibit β-cell mitochondrial dysfunction, low ATP levels and reduced insulin secretion." (PMID 27195491, 2016). "Co-labelling with antibodies against smooth muscle actin to mark the spleen vasculature, and insulin and glucagon to identify pancreatic islets, showed no overall disruptions in tissue morphology in the Down syndrome samples." (PMID 26658127, 2015).
Hyperammonemia (14 papers, 2013 to 2025). An increased concentration of ammonia in the blood. "Beneficial effects associated with TMAO include potential protection from hyperammonemia and glutamate neurotoxicity, alleviation of endoplasmic reticulum stress, and improved glucose homeostasis by stimulating insulin secretion by pancreatic cells." (PMID 29678198, 2018). "Inconsistent scientific reports suggest that hyperammonemia impairs blood glucose and insulin secretion." (PMID 35624703, 2022). "Cessation of protein consumption, higher caloric intake, insulin, carnitine, vitamins, and sodium benzoate/phenyl butyrate are used for treatment of hyperammonemia." (PMID 30987345, 2019). "HI-HA is a syndrome of congenital hyperinsulinism and hyperammonemia that has been related to activating mutations affecting GDH (glutamate dehydrogenase), a participant in the insulin secretion pathway." (PMID 23762547, 2013). "These defects cause GDH to become insensitive to inhibition, resulting in excess ammonia production and insulin release and neurological sequelae from hypoglycemic insults and hyperammonemia." (PMID 23762547, 2013). "Current clinical guidelines for hyperammonemia management include limiting protein consumption and caloric intake ≥ 100 kcal/kg and pharmacological interventions (insulin, L-arginine, L-carnitine, vitamins, nitrogen scavengers (benzoate and/or phenylbutyrate), and peroral carboxyglutamate)." (PMID 39523291, 2025).
Hypoalbuminemia (14 papers, 1978 to 2025). The concentration of albumin in the blood circulation is below the lower limit of normal. "Beyond hypoalbuminemia, an inflammatory response incites the release of growth hormones, glucagon, cortisol, and catecholamines, precipitating insulin resistance and fuel-store mobilization." (PMID 38541789, 2024). "T2DM can lead to decreased serum albumin levels, and insulin is clinically needed to prevent hypoalbuminemia." (PMID 36747238, 2023). "First, diabetic inpatients with hypoalbuminemia are very likely to have depleted insulin reserve and are likely to require early initiation of insulin therapy to prevent ketosis." (PMID 27504458, 2016). "The pathophysiology of refeeding oedema is not entirely understood and is likely to be multifactorial including hypoalbuminemia, hormonal changes, electrolyte imbalance, increased insulin secretion, and the sudden discontinuation of laxatives or diuretics." (PMID 27293884, 2016). "Taken together, the findings suggest that the reduced glucose tolerance in patients with neoplasia is due to impairment of insulin release exhibited predominantly by ill-nourished advanced cancer patients having a moderate to sever degree of hypoalbuminemia." (PMID 698044, 1978). "Clinically, this suggests that hypoalbuminemia is unlikely to significantly affect insulin icodec activity." (PMID 39810242, 2025).
Immunodeficiency (14 papers, 2010 to 2025). Failure of the immune system to protect the body adequately from infection, due to the absence or insufficiency of some component process or substance. "In Drosophila, it has been shown that the inflammatory immune deficiency pathway (IMD) increases Dilp2 expression in insulin producing cells." (PMID 39472660, 2024). "T2D, a disease caused by unresponsiveness to endogenous insulin, functions as an immunodeficiency that predisposes patients for infection." (PMID 28974943, 2017). "Twelve weeks after DMM, we observed alterations in pathways associated with neutrophil trap formation, immunodeficiency, insulin signaling, and calcium signaling in bulk RNA sequencing of the dorsal root ganglia neurons that innervate the knee of FD−/− vs WT mice." (PMID 40585250, 2025). "Thus, more severe immune deficiency at ART initiation was associated with lower insulin sensitivity after three years of ART." (PMID 26636578, 2015). "We thus provide evidence for the hypothesis that trauma in aging and in innate immune-deficiency is linked to insulin signaling." (PMID 20596596, 2010). "We discuss the implication of host signaling pathways such as the Toll, Immune Deficiency (IMD), Janus kinase signal transducer and activator of transcription (JAK/STAT), and Insulin/Insulin Growth Factor/Target of Rapamycin (IIS/TOR) on immune function with aging." (PMID 33946849, 2021).
Ovarian cyst (14 papers, 2013 to 2026). The presence of one or more cysts of the ovary. "Being a potent anti-inflammatory herbal drug, it was anticipated that TC extracts would help in improving insulin balance and decrease the risk of developing ovarian cysts." (PMID 37242122, 2023). "As an anti-inflammatory herb, TC is believed to be extremely effective against PCOS due to the fact that insulin dysregulation and ovarian cysts have a common root cause, i.e., chronic mild inflammation in the tissues." (PMID 37242122, 2023). "This endocrinopathy occurs in the ovaries from an imbalance in hormonal levels of androgens and insulin, causing the formation of ovarian cysts, which can interfere with the ovulation process." (PMID 32759095, 2021). "In PCOS rat models, acupuncture restored regular estrous cycles, reduced the incidence of ovarian cysts and improved the insulin resistant." (PMID 41514462, 2026). "Secondary outcomes included ovarian cyst size and follicle number, menstrual cycle regularity, androgen-related manifestations, anthropometric indices, hormonal parameters, insulin sensitization, and safety." (PMID 41497317, 2025). "A clinical phenotype, including changes in the hypothalamic-pituitary-gonadal axis, ovarian cyst development, skeletal maturation and growth, as well as changes in insulin sensitivity and lipid profile, has been reported in aromatase deficiency." (PMID 30074481, 2019). "The PI3K-Akt pathway disturbance is complicated and multifaceted, which could lead to insulin resistance, abnormal follicle apoptosis and proliferation, and the formation of ovarian cysts." (PMID 38373962, 2024). "The following publication, which was still a review of Lim's CED, suggested that acupuncture may have affected PCOS by increasing blood flow to the ovaries, reducing ovarian volume and number of ovarian cysts, improving insulin sensitivity, lowering cortisol levels, assisting in weight loss, etc." (PMID 36276854, 2022). "IGF secreted by granulosa cells is required for follicle maturation beyond the antral stage; however, high levels of insulin or IGF can be detrimental to follicle development, resulting in polyovular follicles, ovarian cysts, and poor oocyte quality." (PMID 23388061, 2013). "Additionally, the elevated insulin and insulin-like growth factor-1 levels observed in women with PCOS may contribute to the formation of ovarian cysts." (PMID 40802395, 2025).
proliferative diabetic retinopathy (14 papers, 2013 to 2025). Advanced retinopathy due to diabetes mellitus characterized by the formation of new vessels in the retina. "We tested whether this protective INS variant associated with lowered risk for development of proliferative diabetic retinopathy (PDR) and diabetic kidney disease (DKD) as long-term diabetic complications." (PMID 36701305, 2023). "Insulin IT for untreated proliferative diabetic retinopathy (PDR) patients can cause severe and irreversible consequences, so for such patients, the conservative treatment for glycemic control may be much safer." (PMID 33607771, 2021). "There were significant negative/positive correlations between miR-93 or miR-152 and five major metabolic indices, except fasting insulin in proliferative diabetic retinopathy." (PMID 35996507, 2022). "Interestedly, in addition to be upregulated in the AD group, insulin-dependent non-advanced diabetic patients (NAD-i) also showed significant upregulation despite the absence of proliferative diabetic retinopathy." (PMID 36652491, 2023). "In a cross-sectional, multi-centered, hospital-based study, the results showed that there was more prevalent non-proliferative diabetic retinopathy (NPDR) and proliferative diabetic retinopathy (PDR) in insulin-taking than those in non-insulin-taking groups." (PMID 24972631, 2014).
thrombosis (14 papers, 2013 to 2024). "There are additional risk factors with PLEX when compared to the conservative insulin infusion, including the need for venous access and increased risk for infection, hemorrhage, or thrombosis." (PMID 38979030, 2024). "Fasting insulin (FI) is also closely associated with thrombosis." (PMID 38553747, 2024). "And we consider that the reason why there had a relationship between the two in clinical observations may be due to the fact that insulin regulates blood glucose levels and affects thrombosis, which in turn leads to VTE." (PMID 38553747, 2024). "They stayed at that level without any treatment, allowing us to conclude that arterial thrombosis may also affect the pancreatic arteries, impairing insulin secretion and elevating the plasma glucose concentration, as has been found in other studies." (PMID 36423045, 2022). "Therefore, selection of donors using insulin for PTA/PAK transplants, where a significant reduction in thrombosis risk was seen with DIU, may offset the higher risk of thrombosis normally seen in PTA/PAK recipients." (PMID 33665687, 2021). "All other extraordinary findings within this syndrome such as gastric retention, arterial and venous thrombosis, loss of smell, disproportional weight loss, relatively high CRP, hemodynamic stability and the limited need for insulin might be explained by hyperleptinemia." (PMID 32844126, 2020). "A large phase III clinical trial CANTOS (Canakinumab Anti-inflammatory Thrombosis Outcomes Study) is currently recruiting participants to assess whether canakinumab may increase insulin secretion and insulin sensitivity in patients with T2DM (ClinicalTrials.gov NCT01327846)." (PMID 25784780, 2015).
vascular dementia (14 papers, 2008 to 2025). A degenerative vascular disorder affecting the brain. "T2DM is associated with an increased risk of AD and vascular dementia induced by increasing oxidative stress, inflammation, impaired insulin, and amyloid metabolism." (PMID 32198702, 2020). "However, the role and mechanism of insulin in vascular dementia (VD) and its underlying mechanism are unknown." (PMID 37256231, 2023). "Subsequent investigations demonstrated reduced blood glucose levels and increased insulin levels in patients with late onset AD compared to aged controls or to patients with vascular dementia." (PMID 26316990, 2013).
age (13 papers, 2012 to 2025). A temporal measurement of the time period elapsed since an identifiable point in the life cycle of an organism. "NMN supplementation has increased NAD+ biosynthesis, suppressed age-related inflammation, increased insulin sensitivity, improved mitochondrial function, etc.." (PMID 38186577, 2023). "In drosophila, the diminishing of insulin signaling via insulin/insulin-like growth factor /TOR signaling pathway has been proven to ameliorate age-related sleep fragmentation." (PMID 36583849, 2023). "Despite numerous studies of age-related pathologies, data on the contribution of brain insulin resistance and innate immunity components to aging are insufficient." (PMID 33519369, 2020). "These indicate that the insulin sensitivity of these brain regions might gradually decrease with age and lead to age-related brain diseases such as AD and PD." (PMID 33795778, 2021).
alopecia (13 papers, 2011 to 2025). Hair loss usually from the scalp. "The current study also showed that subjects with alopecia differed from the control group in the impact of rosuvastatin on lipids, insulin sensitivity, and levels of cardiometabolic risk factors." (PMID 34064815, 2021). "Individuals with early-onset alopecia were characterized by less pronounced changes in plasma lipids and cardiometabolic risk factors, as well as by a potentially unfavorable effect on insulin sensitivity." (PMID 34064815, 2021). "There has been an increase in the reporting of metabolic abnormalities in patients with alopecia areata, and a recent study confirmed increased serum insulin levels in patients with alopecia areata, as well as higher insulin in those with a greater number of hair loss episodes." (PMID 39628749, 2024). "Contrary to the control subjects, the rosuvastatin treatment of men with alopecia deteriorated insulin sensitivity." (PMID 34064815, 2021). "However, they found that alopecia did not regress after the metabolic state improved following insulin therapy." (PMID 25759758, 2015).